MXRA7 (matrix remodeling associated 7)
Synonyms: FLJ46603; TMAP1; PS1TP1
Tractability: Antibody: UniProt predicts a signal peptide or a membrane-spanning region. PROTAC: ubiquitination databases record sites on it; its protein half-life has been measured.
Gene: Protein-coding gene on chromosome 17 (76,672,551 to 76,711,004, reverse strand). Ensembl gene ENSG00000182534.
Subcellular location: Membrane
Subcellular location (Human Protein Atlas): Endoplasmic reticulum
Gene Ontology:
Biological process: megakaryocyte differentiation
Cellular component: endoplasmic reticulum; membrane
Genetic constraint (gnomAD): Loss-of-function variants: 14 observed, 11.23 expected, observed/expected ratio (o/e) 1.25, 90% interval 0.82 to 1.82. The upper end of that interval is the gene's LOEUF score, 1.82, which puts it in group 6 of 6, group 1 being the genes least tolerant of losing a copy. Missense variants: 67 observed, 70.02 expected, observed/expected ratio (o/e) 0.96, 90% interval 0.79 to 1.17. Synonymous variants: 24 observed, 25.69 expected, observed/expected ratio (o/e) 0.93, 90% interval 0.68 to 1.31.
Homologues: Orthologues: chimpanzee MXRA7 (41% identical).
Diseases named in the same sentence as MXRA7 in open-access papers:
MXRA7 is named in the same sentence as 28 diseases in open-access papers, as found by Europe PMC text mining. Sharing a sentence is not in itself a finding about the gene and the disease. The quoted sentences say what the papers report.
acute lymphoblastic leukemia (2 papers, 2018 to 2023). Leukemia with an acute onset, characterized by the presence of lymphoblasts in the bone marrow and the peripheral blood. "Previous studies noted that MXRA7 was overexpressed in childhood acute lymphoblastic leukemia and in ovarian endometriomas." (PMID 29720975, 2018).
acute kidney injury (1 paper, 2025). Sudden and sustained deterioration of the kidney function characterized by decreased glomerular filtration rate, increased serum creatinine or oliguria. "about the significance of MXRA7 in kidney physiology and related pathological processes were of value to the readers of Renal Failure as well." (PMID 39780515, 2025). "Besides CKD, acute kidney injury (AKI) seemed also to involve MXRA7 in certain to-be-defined manners." (PMID 39780515, 2025).
acute myeloid leukemia (1 paper, 2023). Acute myeloid leukemia (AML) is a group of neoplasms arising from precursor cells committed to the myeloid cell-line differentiation. "Public data in platforms like GEO and Bloodspot showed that MXRA7 was expressed highly in ALL and acute myeloid leukemia (AML)." (PMID 37546710, 2023).
cervical cancer (1 paper, 2022). A primary or metastatic malignant neoplasm involving the cervix. "GNG7, MXRA7, ASB2, and CHMP4C are also involved in the development of lung cancer, gastric cancer, colorectal cancer, and cervical cancer, respectively." (PMID 36225190, 2022).
gastric tumors (1 paper, 2023). "A limited number of studies were conducted regarding the function of this gene so far, and our study suggests that MXRA7 is expressed in stroma-high gastric tumors and may be also involved in remodeling of cancer-associated TME." (PMID 37296997, 2023).
liver disease (1 paper, 2018). "In the current study, the potential role of MXRA7 in liver disease was investigated in mice by utilizing the CCl4-induced liver injury model." (PMID 29720975, 2018).
meningioma (1 paper, 2020). A generally slow growing tumor attached to the dura mater. "This study revealed the identification of phosphorylated sites of several proteins that were found to play a role in meningioma pathobiology by several studies including EPB41L2, NDRG2, SPTB, MAGED2, MXRA7, and nearly 51 Kinases which were also mapped further through Kinome Analysis." (PMID 32974197, 2020).
myopia (1 paper, 2024). "Eight pairs (protein-coding genes TOM1L2, MXRA7, RHPN2, and HINT1 for senile cataract, WARS1 and TDRD7 for AMD, STAT6 for myopia, and TPPP3 for DR) are newly reported in this study." (PMID 39408566, 2024).
neuroblastoma (1 paper, 2019). Neuroblastoma (NB) is the most common solid, extracranial childhood tumor. "Importantly, chromosome 17q segmental gain and high levels of JMJD6, but not 17q numerical gain or high levels of MXRA7, the gene immediately upstream of JMJD6 at chromosome 17qter, in neuroblastoma tissues correlate with poor patient prognosis." (PMID 31346162, 2019).
psoriasis (1 paper, 2025). An autoimmune condition characterized by red, well-delineated plaques with silvery scales that are usually on the extensor surfaces and scalp. "Beyond its roles in the immune system and tissue regeneration, MXRA7 has also been linked to diseases such as psoriasis, liver injury, and cancer." (PMID 40459788, 2025). "Ning and colleagues discovered that MXRA7 may negatively regulate the development of psoriasis by altering the expression or redistribution of keratinocytes." (PMID 40459788, 2025).
Vertigo (1 paper, 2022). An abnormal sensation of spinning while the body is actually stationary. "Fetal brain-based TWAS identified 20 cis-regulated expression genes associated with vertigo, such as MXRA7 (PTWAS = 0.006), MSH3 (PTWAS = 0.018), and DHFR (PTWAS = 0.038)." (PMID 36519156, 2022).
cancer (4 papers, 2018 to 2025). A tumor composed of atypical neoplastic, often pleomorphic cells that invade other tissues. "Future work should explore MXRA7’s molecular mechanisms in immune diseases, fibrosis, and cancer, advancing its potential as a therapeutic target." (PMID 40459788, 2025). "In an effort to characterize the functions of MXRA7, our lab had found that MXRA7 was involved in the pathological process of ocular inflammatory models and MXRA7 might play a role in tissue injury, wound healing, and cancer (manuscripts under review)." (PMID 29720975, 2018). "Increasingly, literature suggests that MXRA7 possesses diverse biological functions and could become an important target for the treatment of diseases characterized by matrix remodeling, such as fibrosis, cardiovascular diseases, and certain cancers." (PMID 40459788, 2025). "In addition, it was found that MXRA7 may be involved in the treatment of some tumors, but a comprehensive analysis of the role of MXRA7 in cancer and its value in immunotherapy and drug resistance regulation has not been fully explored." (PMID 40459788, 2025).
cardiovascular disease (2 papers, 2024 to 2025). "Research by influential authors like Frangogiannis NG and Ahmed A has significantly advanced understanding of MXRA7’s involvement in cardiovascular diseases and matrix remodeling, providing foundational theoretical support for its broader implications." (PMID 40459788, 2025). "The role of MXRA7 (matrix-remodeling-associated protein 7) in potentially modulating RHR and cardiovascular disease is less known; but it has previously been associated with a cardiorespiratory fitness polygenic risk score." (PMID 38969939, 2024).
tumor (2 papers, 2022 to 2024). "In the 24 pairs of samples including tumor and normal tissues, most expressions of GNG7 and MXRA7 in tumor tissues minus their expressions in normal samples were less than 0, indicating that the two most significant genes have higher expressions in normal tissues." (PMID 36225190, 2022). "In summation, the molecules ZNF165, MXRA7, CEMIP, ARL4C, and CERCAM collectively represent prospective therapeutic nexus points in impeding tumor advancement." (PMID 39624211, 2024). "We can find that the expression of GNG7, MXRA7, ASB2, and PDGFD in tumor samples is significantly lower than that in normal samples, while the expression of RPS6KA1, CHMP4C, APOL1, and LYPD3 is reverse." (PMID 36225190, 2022).
infection (1 paper, 2015). The state of being infected such as from the introduction of a foreign agent such as serum, vaccine, antigenic substance or organism. "For example, two novel intergenic splicing events occurred between exons of SRSF2, JMJD6 and MXRA7 late in infection." (PMID 25989971, 2015).
MXRA7 also shares sentences with these, for which no sentence is quoted: Arthritis (1 paper); asthma (1); atherosclerosis (1); chronic kidney disease (1); colon cancer (1); colorectal cancer (1); gastric cancer (1); immune diseases (1); lung carcinoma (1); renal carcinoma (1); renal diseases (1); senile cataract (1); virus infections (1).